RN7SL378P (RNA, 7SL, cytoplasmic 378, pseudogene)
Gene: Miscellaneous RNA gene on chromosome 5 (82,078,427 to 82,078,724, forward strand). Ensembl gene ENSG00000265684.
Homologues: Orthologues: chimpanzee Metazoa_SRP (98% identical), macaque Metazoa_SRP (94% identical). Paralogues in human: RN7SL1 (84% identical), RN7SL3 (84% identical), RN7SL2 (83% identical), RN7SL296P (82% identical), RN7SL126P (82% identical), RN7SL493P (81% identical), RN7SL566P (80% identical), RN7SL597P (80% identical), RN7SL664P (80% identical), RN7SL219P (80% identical), RN7SL322P (80% identical), RN7SL41P (80% identical), and 703 more.